DLC1 (DLC1 Rho GTPase activating protein)
Diseases named in the same sentence as DLC1 in open-access papers (continued):
Sharing a sentence is not in itself a finding about the gene and the disease.
melanoma (4 papers, 2020 to 2024). A malignant, usually aggressive tumor composed of atypical, neoplastic melanocytes. "The loss of DLC-1 protein function in melanoma tissue samples significantly promotes melanoma’s aggressiveness and deteriorates patients’ prognosis." (PMID 37013489, 2023). "To further unravel the molecular mechanisms by which DLC1 associates with FOXK1 to regulate melanoma metastasis, we undertook RNA-seq analysis of both DLC1 KD and FOXK1 KD A375 cells to identify changes in gene expression compared with scrambled control." (PMID 32214200, 2020). "Nevertheless, our data demonstrate that nuclear DLC1 is clinically associated with FOXK1 to promote melanoma invasion and metastasis through cooperative activation of MMP9 expression." (PMID 32214200, 2020). "Our results provide a new paradigm of the underlying mechanism by which a well-known tumor-suppressor DLC1 functions in the nucleus as an oncogene in melanoma." (PMID 32214200, 2020). "Here, we demonstrate that DLC1, which is known to function as a tumor suppressor in various cancer types, plays oncogenic roles in melanoma, through the association of transcription factor FOXK1 in the nucleus for cooperative activation of MMP9 expression to promote invasion and metastasis." (PMID 32214200, 2020). "Besides, immunofluorescence staining showed predominant nuclear localization of endogenous DLC1 and FOXK1 in melanoma cells, suggesting that DLC1 is likely to associate with FOXK1 in the nucleus." (PMID 32214200, 2020). "However, a previous report showed that loss of DLC1 expression in primary cutaneous and metastatic melanomas was associated with poor survival, suggesting that DLC1 might inhibit melanoma growth and progression." (PMID 32214200, 2020). "High levels of DLC1 expression are detected in most melanoma tissues, and functional studies have revealed that DLC1 is both necessary and sufficient for melanoma growth and metastasis." (PMID 38873887, 2024). "Functional studies unveiled that DLC1 was both required and sufficient for melanoma growth and metastasis." (PMID 32214200, 2020). "In summary, this is the first report showing nuclear-localized DLC1 to function as an oncogene through FOXK1 recruitment to cooperatively transactivate MMP9 expression for promoting melanoma invasion and metastasis." (PMID 32214200, 2020). "Conversely, OE of WT-DLC1 or K714E-DLC1 in low DLC1-expressing UACC-827 melanoma cells significantly promoted colony formation, invasion, and proliferation compared with vehicle control." (PMID 32214200, 2020). "To further examine DLC1 protein expression in melanoma tissue samples, we performed immunofluorescence in a melanoma tissue microarray composed of 45 cores of primary cutaneous melanomas." (PMID 32214200, 2020). "Here, we found elevated levels of DLC1 mRNA in the majority of melanoma tissues where DLC1 protein was localized in both the nuclei and the cytoplasm." (PMID 32214200, 2020). "Conversely, we did not observe significant alteration of RHOA activity and its downstream events in both DLC1 KD and OE melanoma cells." (PMID 32214200, 2020). "Most of the melanomas showing strong nuclear DLC1 were MELAN A positive (19/29; 65.5%), whereas a small portion of MELAN A+ cells exhibited weak nuclear DLC1 (10/29; 34.5%)." (PMID 32214200, 2020). "Nevertheless, our loss- and gain-of-function assays in vitro and in vivo provide strong evidence to support an oncogenic role of DLC1 in determining the tumorigenicity and metastatic behavior of melanoma." (PMID 32214200, 2020). "RNA-sequencing profiling studies further revealed MMP9 as a direct target of FOXK1 through DLC1-regulated promoter occupancy for cooperative activation of MMP9 expression to promote melanoma invasion and metastasis." (PMID 32214200, 2020). "Altogether, these data indicate that DLC1 is required to promote the invasiveness, tumorigenicity, and proliferation of melanoma cells in a RHOA-independent manner." (PMID 32214200, 2020).
melanoma (continued). "These staining results are consistent with previous findings showing strong nuclear DLC1 staining in most of the primary melanomas (56%) from tissue microarrays." (PMID 32214200, 2020). "To evaluate the role of DLC1 in melanoma metastasis, we performed lung colonization assay by injecting scrambled control, DLC1 KD1 and KD2 cells into the tail vein of NOD/SCID mice." (PMID 32214200, 2020). "Together, our results not only unravel a mechanism by which nuclear DLC1 functions as an oncogene in melanoma but also suggest an unexpected role of RhoGAP protein in transcriptional regulation." (PMID 32214200, 2020). "Altogether, these results suggest that FOXK1 functions as an oncogene in melanoma progression likely through partnering with DLC1 in the nucleus." (PMID 32214200, 2020). "Here we revealed that high DLC1 expression was detected in most of the melanoma tissues where it was localized in both the nuclei and the cytoplasm." (PMID 32214200, 2020). "We demonstrated that FOXK1 was crucial for DLC1 nuclear translocation and retention to orchestrate oncogenic programs in melanoma." (PMID 32214200, 2020). "Similarly, OE of both DLC1 and FOXK1 also further enhanced the invasiveness of DLC1 KD melanoma cells than OE of each factor in vitro." (PMID 32214200, 2020). "A Rho GTPase-activating protein (RhoGAP), deleted in liver cancer 1 (DLC1), is known to function as a tumor suppressor in various cancer types; however, whether DLC1 is a tumor-suppressor gene or an oncogene in melanoma remains to be clarified." (PMID 32214200, 2020). "We found DLC1 and a melanoma marker MELAN A exhibited high correlation of their expression (χ2 = 4.546, p < 0.033) in a large percentage of melanomas (29/45; 64.4%) compared with other specimens expressing either DLC1 (5/45; 11.1%) or MELAN A alone (6/45; 13.3%) and neither of them (5/45; 11.1%)." (PMID 32214200, 2020). "Furthermore, DLC1 was expressed at higher levels in a panel of malignant melanoma cell lines than epidermal melanocytes." (PMID 32214200, 2020). "In addition to the detection of cytoplasmic DLC1 in all samples analyzed, we also observed strong (21/34; 61.8%) and weak (13/34; 38.2%) nuclear DLC1 expression in melanoma cells." (PMID 32214200, 2020). "Since a substantial number of melanoma patients had DLC1 copy-number gain, this allelic alteration may be a major factor driving the elevation of DLC1 expression in this tumor type." (PMID 32214200, 2020). "Our findings detected strong and weak levels of nuclear DLC1 expression in the majority of primary and metastatic melanomas, whereas previous studies revealed a marked reduction in the percentage of samples with nuclear DLC1 expression in metastatic melanomas compared with primary melanomas." (PMID 32214200, 2020). "Whether distinct regulatory mechanisms contribute to the increased expression of DLC1 in melanoma remain to be elucidated." (PMID 32214200, 2020). "Importantly, DN-DLC1 is not sufficient to promote the invasive behavior of DLC1LOW cells like nuclear WT-DLC1, further ruling out the contribution of cytoplasmic DLC1 to govern melanoma growth and progression." (PMID 32214200, 2020). "To identify nuclear cofactors of DLC1 that may unravel the mechanisms by which DLC1 promotes melanoma progression, we performed immunoprecipitation for endogenous DLC1 in A375 cell lysates followed by mass spectrometry analysis." (PMID 32214200, 2020). "Similarly, DLC1 was also found to be localized in both the cytoplasm and nuclei of metastatic melanomas but how this subcellular localization of DLC1 regulates melanoma progression is largely unknown." (PMID 32214200, 2020). "Whether DLC1 indeed functions as a tumor suppressor in melanoma remains to be determined." (PMID 32214200, 2020).
melanoma (continued). "However, cytoplasmic DN-DLC1 was ineffective in inhibiting melanoma invasion, antagonizing the oncogenic functions of ectopic WT-DLC1 and K714E-DLC1 in UACC-827 cells, and restoring migration defects of DLC1 KD A375 and WM266-4 cells, ruling out the oncogenic role of cytoplasmic DLC1." (PMID 32214200, 2020). "Taken together, the data suggest that DLC1 and FOXK1 function in a cooperative manner to transactivate MMP9 promoter activity as well as MMP9 functions downstream of DLC1 and FOXK1 to promote melanoma invasion in vitro." (PMID 32214200, 2020). "Our results identified MMP9 as one of the downstream targets to mediate the roles of DLC1 and FOXK1 in promoting melanoma cell invasion and metastasis." (PMID 32214200, 2020). "To correlate the clinical relevance of DLC1, FOXK1, and MMP9 expression, we analyzed their expression in a melanoma tissue microarray composed of 50 cores of metastatic melanomas." (PMID 32214200, 2020). "Consistently, DLC1, FOXK1, and MMP9 exhibited a high correlation of expression in melanoma patients’ samples and cell lines." (PMID 32214200, 2020). "Consistent with its expression change in RNA-seq, we confirmed the downregulation of MMP9 at the mRNA and protein levels in both DLC1 KD and FOXK1 KD melanoma cells." (PMID 32214200, 2020). "To further investigate whether the observed increase in DLC1 expression levels in cutaneous melanomas functionally promotes their progression, we overexpressed (OE) wild-type DLC1 (WT-DLC1) and K714E-DLC1 (RhoGAP deficient mutant) in A375 and WM266-4 melanoma cells." (PMID 32214200, 2020). "Mechanistically, DLC1 was essential for FOXK1 occupancy to the promoter region of MMP9, and both DLC1 and FOXK1 acted cooperatively to transactivate MMP9 expression for melanoma invasion and metastasis." (PMID 32214200, 2020). "To further substantiate the cooperative action of the DLC1–FOXK1 complex in regulating MMP9 expression and promoting melanoma invasiveness, we examined the ability of DLC1 OE, FOXK1 OE, and both to restore MMP9 expression and melanoma invasion in DLC1 KD cells." (PMID 32214200, 2020). "Follow up study to elucidate the molecular mechanisms that confer DLC1 with oncogenic activity in melanoma but not in other cancer types will provide new insight into the context-dependent role of DLC1." (PMID 32214200, 2020). "Functional assays showed that nuclear, but not cytoplasmic, localization of DLC1 promoted growth and invasion of melanoma cells in a RhoGAP-independent manner." (PMID 32214200, 2020). "One of the most unanticipated findings in this study is the increased expression of DLC1 in melanoma patient samples and cell lines compared with normal tissues and melanocytes, respectively." (PMID 32214200, 2020). "Indeed, endogenous DLC1 was found to be localized in the cytoplasm of FOXK1 KD1 and KD2 melanoma cells compared with its nuclear localization in the scrambled control, suggesting that FOXK1 is required for retaining DLC1 in the nucleus." (PMID 32214200, 2020). "It remains unclear as to why DLC1 OE failed to inhibit RHOA activity in melanoma cells." (PMID 32214200, 2020). "In addition, the lack of increased RHOA activity in DLC1 KD melanoma cells could be due to predominant nuclear localization of endogenous DLC1, which was shown to be less efficient in mediating RHOA inhibition in other cancer cell types compared with cytoplasmic DLC1." (PMID 32214200, 2020). "Importantly, DLC1 expression levels remained unaltered in both FOXK1-depleted and FOXK1 OE melanoma cells, indicating that DLC1 expression is not regulated by FOXK1." (PMID 32214200, 2020).
metastatic disease (4 papers, 2010 to 2025). "Low DLC1 expression also predicts poor therapeutic efficiency of fluoropyrimidine/oxaliplatin in adjuvant chemotherapy and was associated with advanced, metastatic disease and shortened time to recurrence and overall survival." (PMID 35963849, 2022). "Methylation of RUNX3, SCGB3A1, SFRP4, and DLC1 was significantly associated with the extent of the disease when comparing localized versus metastatic tumors." (PMID 20849603, 2010). "When comparing methylation rates in localized tumors versus metastatic disease, the methylation of RUNX3 (p = 0.013), SCGB3A1-2 (p = 0.008), SFRP4-2 (p = 0.022), and DLC1 (p = 0.016) was significantly associated with the presence of metastatic disease." (PMID 20849603, 2010). "Hence, higher E-cad expression and, as a result, a partial EMT phenotype upon DLC1 loss may contribute to cellular plasticity, in normal development and metastatic diseases." (PMID 40354489, 2025). "In this study, even though the high expression of miR-200c-3p was found to cause downregulation of a tumor suppressor gene DLC1, at the same time it also led to upregulation of CDH1 expression in both primary and metastatic tumor cells." (PMID 34071861, 2021).
Obesity (4 papers, 2015 to 2022). Accumulation of substantial excess body fat. "Moreover, DLC1 is involved in the differentiation of white and brown adipocytes in mouse embryonic fibroblasts, constituting an important component of the metabolic dysfunction which can cause obesity and T2DM." (PMID 32956382, 2020). "Furthermore, eight of the 17 CpG sites reside in genes (FSTL1, SORCS2, NRF1, DLC1, PPARGC1B, CHN2, NXPH1) that have prior known associations with obesity, diabetes, and the insulin pathway." (PMID 28068899, 2017).
colon adenocarcinoma (3 papers, 2020 to 2024). "We collected and concentrated DLC1-overexpressed SW1116 cell CM to culture wild-type colon adenocarcinoma cell lines SW1116 and HCT116." (PMID 36185184, 2022). "We established stable colon adenocarcinoma cell line with overexpression of DLC1 in SW1116 via lentivirus infection." (PMID 36185184, 2022). "In contrast, the expression of DLC1 was down‐regulated in various tumours (liver hepatocellular carcinoma, bladder urothelial carcinoma, colon adenocarcinoma, etc) compared with normal tissues." (PMID 32725802, 2020). "In summary, the present study showed that DLC1 interacted with GRP78 to increase the release of MANF, which inhibited the migration of wild-type colon adenocarcinoma cells." (PMID 36185184, 2022). "Here, we found that DLC1 was downregulated in CRC and overexpressed DLC1 promoted the secretion of MANF to inhibit colon adenocarcinoma cell migration." (PMID 36185184, 2022).
congenital heart disease (3 papers, 2014 to 2025). A heart disease that is present at birth. "DLC1 deletion is embryonic lethal and linked to heart development defects, and several DLC1 variants have been identified in a Chinese cohort for sporadic congenital heart disease." (PMID 40911671, 2025). "DLC1 was recently linked to congenital heart disease in the Chinese population." (PMID 33766035, 2021).
diabetes (3 papers, 2017 to 2022). "We further explored whether the expression of DLC1 was related to histological type, histological grade, clinical stage, BMI, diabetes, event, and menopause status." (PMID 35223504, 2022).
endometrial cancer (3 papers, 2020 to 2025). Primary or metastatic malignant neoplasm involving the endometrium (mucous membrane that lines the endometrial cavity). "The levels of both NSUN5P2 and DLC1 in the tissues of 546 endometrial cancer patients showed significant differences compared to those in the normal control group." (PMID 40708858, 2025). "Upon searching the ULCAN website, we further discovered that the levels of both NSUN5P2 and DLC1 in the tissues of 546 endometrial cancer patients showed significant differences compared to those in the normal control group." (PMID 40708858, 2025). "Deleted in liver cancer 1 (DLC1) is confirmed as a metastasis suppressor gene in endometrial carcinoma (EC)." (PMID 35223504, 2022). "Univariate analysis and multivariate analysis of the correlation of DLC1 expression with OS among endometrial carcinoma patients." (PMID 35223504, 2022). "We download a dataset [Endometrial Cancer] of 95 patients with UCEC (83 endometrioid and 12 serous tumors) from the cBioPortal database to investigate the endogenous protein levels of DLC1." (PMID 35223504, 2022).
lymph node metastasis (3 papers, 2013 to 2020). "The low expression of DLC-1 was significantly associated with advanced FIGO stage, ascites and lymph node metastasis." (PMID 26260454, 2015). "The expression of DLC1 and PAI-1 were significantly associated with FIGO stage and lymph node metastasis in ovarian carcinoma." (PMID 23988121, 2013). "In ovarian carcinoma, the expression of DLC1 was significantly associated with advanced FIGO stage, ascites and positive lymph node metastasis, whereas PAI-1 protein was closely related with advanced FIGO stage, poor histological differentiation and lymph node metastasis." (PMID 23988121, 2013). "Partial Correlate analysis showed the expression of DLC1 was negatively related with FIGO stage (P = 0.015), ascites (P = 0.043), lymph node metastasis (P = 0.021), but positively related with prognosis (P = 0.009)." (PMID 23988121, 2013).
nephrotic syndrome (3 papers, 2018 to 2020). A collection of symptoms that include severe edema, proteinuria, and hypoalbuminemia; it is indicative of renal dysfunction. "DLC1 is another example of a Rho GTPase-activating protein in which mutations cause nephrotic syndrome." (PMID 32708597, 2020). "In humans, DLC1 defects, depending on the variant, have been associated with autosomal dominant congenital heart disease or nephrotic syndrome." (PMID 32344861, 2020). "Since DLC1 is regulated by cyclic dependent kinase 20 (CDK20) and tensin-2 (TNS2), mutations in TNS2 and cyclin-dependent kinase 20 (CDK20) are also causative in some cases of nephrotic syndrome." (PMID 32708597, 2020). "Interestingly, a distinct disease phenotype of partially treatment sensitive nephrotic syndrome (pTSNS) occurred in four of the five individuals with recessive TNS2 and in two of the four individuals with DLC1 mutations." (PMID 29773874, 2018).
ovarian tumor (3 papers, 2011 to 2022). "For example, in ovarian tumor cells deficient in Dlc1 (responsible for phosphorylation of nonmuscle IIA myosin), elongation is promoted, suggesting that an increase in motor velocity indeed facilitates greater cell elongation." (PMID 32896767, 2020). "In the present study, we found that the cytoplasmic expression of DLC1 protein was significantly decreased or absent in EOC when compared with other types of ovarian tumor tissues and normal ovarian tissues." (PMID 22272086, 2011). "This could indicate that, while in other tumor types StarD13 is the main GAP for RhoA due to the absence of DLC1, in ovarian tumors DLC1 mainly drives this inhibition." (PMID 34958986, 2022).
breast tumor (2 papers, 2015 to 2018). "Transfection of Dlc1 into deficient breast tumor cells will inhibit both in vitro and in vivo tumor cell growth." (PMID 26353792, 2015). "These analyses suggest that downregulation of DLC1 in majority of breast tumors is not due to mutations or methylation." (PMID 30278072, 2018). "Reduced or absent expression of Dlc1 has been frequently found in primary breast tumors and cell lines." (PMID 26353792, 2015).
gastric disease (2 papers, 2013 to 2023). "Further, the study demonstrated that DLC1 is transcriptionally down-regulated by CagA, which promotes oncogenic effects and constitutes DLC1 as an early molecular marker for Helicobacter-related gastric disease." (PMID 36984515, 2023).
glioma (2 papers, 2022 to 2025). A benign or malignant brain and spinal cord tumor that arises from glial cells (astrocytes, oligodendrocytes, ependymal cells). "In high-risk gliomas, recurrent CNVs—such as chromosome 7/12 amplifications (EGFR, CDK4/MDM2) and chromosome 1/8/13 deletions (CHD5, DLC1, RB1)—play pivotal roles in promoting proliferation, immune evasion, and DNA repair defects." (PMID 40636690, 2025). "This study investigated the function of circular RNA DLC1 (circDLC1) in the malignant proliferation of glioma cells." (PMID 35474040, 2022).